DNAJB7 (DnaJ heat shock protein family (Hsp40) member B7)
Description:
Probably acts as a co-chaperone.
Synonyms: HSC3; DJ5
Tractability: PROTAC: ubiquitination databases record sites on it.
Gene: Protein-coding gene on chromosome 22 (40,859,549 to 40,862,113, reverse strand). Ensembl gene ENSG00000172404.
Subcellular location (Human Protein Atlas): Nucleoplasm; Cytosol; Golgi apparatus
Gene Ontology:
Molecular function: protein-folding chaperone binding; protein folding chaperone; Hsp70 protein binding
Biological process: protein folding
Cellular component: cytoplasm; nucleus
Genetic constraint (gnomAD): Loss-of-function variants: 3 observed, 3.07 expected, observed/expected ratio (o/e) 0.98, 90% interval 0.42 to 1.85. That is too few expected variants to judge how well the gene tolerates losing a copy. Missense variants: 420 observed, 378.54 expected, observed/expected ratio (o/e) 1.11, 90% interval 1.02 to 1.2. Synonymous variants: 128 observed, 135.22 expected, observed/expected ratio (o/e) 0.95, 90% interval 0.82 to 1.1.
Homologues: Orthologues: chimpanzee DNAJB7 (98% identical), macaque DNAJB7 (94% identical), mouse Dnajb7 (74% identical), rabbit DNAJB7 (73% identical), rat Dnajb7 (68% identical), tropical clawed frog dnajb2 (38% identical), zebrafish dnajb6b (35% identical), zebrafish dnajb1b (28% identical), zebrafish dnajb1a (27% identical), Drosophila melanogaster CG5001 (26% identical), Caenorhabditis elegans dnj-24 (26% identical), Drosophila melanogaster DnaJ-1 (26% identical), and 8 more. Paralogues in human: DNAJB6 (58% identical), DNAJB2 (36% identical), DNAJB8 (36% identical), DNAJB4 (29% identical), DNAJB1 (28% identical), DNAJB5 (27% identical), DNAJB13 (24% identical), DNAJB11 (23% identical), DNAJB12 (21% identical), DNAJB9 (20% identical), DNAJB14 (19% identical).
Diseases named in the same sentence as DNAJB7 in open-access papers:
DNAJB7 is named in the same sentence as 12 diseases in open-access papers, as found by Europe PMC text mining. Sharing a sentence is not in itself a finding about the gene and the disease. The quoted sentences say what the papers report.
infertile (1 paper, 2023). "Similar to DNAJB7, Dnajb8 is predominantly in haploid male germ cells but dispensable for spermatogenesis, although Dnajb8 transcripts are downregulated in the spermatozoa of infertile men compared to those of fertile men." (PMID 37004113, 2023).
Insulin resistance (1 paper, 2025). Increased resistance towards insulin, that is, diminished effectiveness of insulin in reducing blood glucose levels. "DNAJB7, a gene with a nonsynonymous mutation under selection in the central MI populations, is a member of the DnaJ family that has been related to the pathogenesis of insulin resistance and Type 2 diabetes (T2D) mellitus." (PMID 40070201, 2025).
cancer (4 papers, 2016 to 2025). A tumor composed of atypical neoplastic, often pleomorphic cells that invade other tissues. "DNAJB7, known as an evolutionarily conserved DNAJB protein, was found to be a novel cancer-testis (CT) antigen due to the failure to detect DNAJB7 protein in normal tissues except for the testis." (PMID 37004113, 2023). "Here, we investigated the function of the cancer-testis gene Dnajb7 in spermatogenesis and male fertility." (PMID 37004113, 2023).
DNAJB7 also shares sentences with these, for which no sentence is quoted: tumor (7 papers); oral squamous cell carcinoma (2); congenital glaucoma (1); hypopharyngeal cancer (1); Obesity (1); oral cancer (1); oral cavity cancer (1); Parkinson disease (1); Pythiosis (1).